Y_RNA (Y RNA )
Gene: Miscellaneous RNA gene on chromosome 4 (59,533,786 to 59,533,898, forward strand). Ensembl gene ENSG00000199780.
Homologues: Orthologues: chimpanzee Y_RNA (96% identical). Paralogues in human: RNY1 (84% identical), Y_RNA (84% identical), Y_RNA (82% identical), RNY1P11 (81% identical), Y_RNA (81% identical), Y_RNA (80% identical), RNY1P8 (79% identical), Y_RNA (79% identical), Y_RNA (78% identical), RNY1P5 (77% identical), RNY1P7 (77% identical), Y_RNA (77% identical), and 95 more.